FNDC5 (fibronectin type III domain containing 5)
Description:
[Irisin]: Mediates beneficial effects of muscular exercise. Induces browning of white adipose tissue by stimulating UCP1 expression, at least in part, via the nuclear receptor PPARA.
Synonyms: FRCP2; irisin
Tractability: Antibody: UniProt places it where antibodies can reach, with high confidence; UniProt predicts a signal peptide or a membrane-spanning region; its Gene Ontology location is reachable by antibodies, with medium confidence.
Gene: Protein-coding gene on chromosome 1 (32,862,268 to 32,872,482, reverse strand). Ensembl gene ENSG00000160097.
Subcellular location: Cell membrane (Fibronectin type III domain-containing protein 5); Peroxisome membrane; Secreted (Irisin)
Gene Ontology:
Biological process: positive regulation of brown fat cell differentiation; response to muscle activity
Cellular component: extracellular region; plasma membrane; endoplasmic reticulum; peroxisomal membrane
Genetic constraint (gnomAD): Loss-of-function variants: 9 observed, 19.47 expected, observed/expected ratio (o/e) 0.46, 90% interval 0.28 to 0.81. The upper end of that interval is the gene's LOEUF score, 0.81, which puts it in group 3 of 6, group 1 being the genes least tolerant of losing a copy. Missense variants: 203 observed, 253.66 expected, observed/expected ratio (o/e) 0.8, 90% interval 0.71 to 0.9. Synonymous variants: 85 observed, 96.74 expected, observed/expected ratio (o/e) 0.88, 90% interval 0.74 to 1.05.
Homologues: Orthologues: chimpanzee FNDC5 (99% identical), macaque FNDC5 (99% identical), mouse Fndc5 (98% identical), rat Fndc5 (98% identical), pig FNDC5 (95% identical), dog FNDC5 (94% identical), guinea pig FNDC5 (84% identical), zebrafish fndc5a (68% identical), zebrafish fndc5b (67% identical), rabbit FNDC5 (66% identical). Paralogues in human: FNDC4 (47% identical).
Diseases named in the same sentence as FNDC5 in open-access papers:
FNDC5 is named in the same sentence as 144 diseases in open-access papers, as found by Europe PMC text mining. Sharing a sentence is not in itself a finding about the gene and the disease. The quoted sentences say what the papers report.
Obesity (83 papers, 2012 to 2026). Accumulation of substantial excess body fat. "Conversely, polymorphisms in the FNDC5 gene have been linked to other pathologies, particularly diseases related to physical inactivity such as obesity, diabetes, and metabolic syndrome." (PMID 38139046, 2023). "Irisin/FNDC5 is not only involved in metabolic functions and linked to conditions such as diabetes, obesity, and cerebrovascular disease but also plays a crucial role in mediating the benefits of physical exercise." (PMID 38139046, 2023). "The results showed that BS21 treatment dramatically upregulated the mRNA expression of SIRT1 (Sirt1), PGC-1α (Ppargc1a), and FNDC5/irisin (Fndc5), due to increased muscle weight loss by obesity." (PMID 35276805, 2022). "Second, we evaluated only one polymorphism in the FNDC5 gene; many other genes are known to be involved in the development of obesity." (PMID 34574727, 2021). "This association suggests that FNDC5 is beneficial for the treatment of obesity, diabetes, and a variety of pathological conditions characterized by an imbalance in energy expenditure." (PMID 34574727, 2021). "Further, high FNDC5/irisin levels in middle-aged males with grade 1 obesity were associated with an improved metabolic profile, low risk of developing T2DM, and decreased serum LPS." (PMID 31428053, 2019). "The NFκB activation indicated by increased p65 in nucleus and reduced p65 in cytoplasm, and the enhanced phosphorylation level of ERK suggested that FNDC5 deficiency aggravated cardiac inflammation in obesity." (PMID 30940158, 2019). "Irisin, a type I membrane protein encoded by the Fndc5 gene and secreted by skeletal muscle after exercise, participates in mitochondrial biogenesis and adipose tissue browning and improves obesity and glucose homeostasis." (PMID 31133682, 2019). "Analyses of FNDC5 SNPs showed that: 1) The rs3480 GG associates with decreased risk of obesity (p = 0.005; odds ratio: 0.48) and lower body mass index (BMI) values (p = 0.03)." (PMID 26968837, 2016). "Until now, only three previous genetic studies have investigated the association of common SNPs in FNDC5 with obesity, insulin sensitivity and glucose metabolism." (PMID 26968837, 2016). "The increase in FNDC5 gene expression caused by obesity may serve as a compensatory mechanism to cope with the condition." (PMID 40071055, 2024). "This study indicated a significant reduction in FNDC5 expression in the soleus muscle of obese rats after six weeks of cold water exposure, which may represent a compensatory mechanism against the heightened FNDC5 expression associated with obesity." (PMID 40071055, 2024). "However, the expression levels of irisin have also been found reduced in age-associated sarcopenia independently from obesity and osteoporosis, as well as exacerbated muscle wasting being reported in FNDC5 KO aging mice." (PMID 39769243, 2024). "Thus, the lower the levels of FNDC5 in patients with obesity, the higher their susceptibility to SARS-CoV-2 due to the increased number of entry points and the higher the visceral adipocytes death due to inflammatory pathways." (PMID 37408184, 2023). "In addition to its therapeutic targets for obesity-associated maladies, FNDC5 is also involved in other metabolic diseases." (PMID 33790964, 2021). "Moreover, a potential role of irisin in protecting against obesity and associated disorders was proposed based on the fact that forced FNDC5 overexpression in both lean and diet-induced obese mice provoked the browning of white adipose tissue (WAT)." (PMID 26961074, 2016). "Results showed that rs3480, an intronic variant in FNDC5 gene, is protective against obesity." (PMID 26968837, 2016). "Thus, we examined the association between these metabolic parameters, known to be altered in T2DM and obesity, and FNDC5 gene variants." (PMID 26968837, 2016).
Obesity (continued). "Briefly, exercise causes an increase circulating irisin protein levels and/or FNDC5 mRNA expression in some, but not all studies, whereas, obesity has either a positive or a negative association with irisin/FNDC5." (PMID 25289190, 2014). "Interestingly, it may be increased in patients with metabolic disturbances, such as obesity; and weight loss and fat mass reduction can be responsible for a decrease in FNDC5/irisin concentration." (PMID 27828992, 2016). "Research indicates that physical activity promotes the expression of PPARγ coactivator-1 (PGC1) and FNDC5 in skeletal muscle, leading to the production of thermogenic cells that contribute to the prevention of obesity and metabolic syndrome (MetS)." (PMID 39539896, 2024). "First, we examined how obesity affects the expression of the fibronectin type-III domain containing 5 (FNDC5) and uncoupling protein 1 (UCP1) genes in male Wistar rats." (PMID 40071055, 2024). "Irisin is derived from its precursor, fibronectin type III domain-containing protein 5 (FNDC5), which is under expressed in obesity and NAFLD." (PMID 36834782, 2023). "In the context of obesity-induced chronic inflammation, the administration of exogenous FNDC5 was found to inhibit LPS-induced differentiation of M1-type macrophages, while the deficiency of FNDC5 promoted such differentiation." (PMID 37047523, 2023). "They found that FNDC5 overexpression attenuates adipose tissue inflammation in obesity by inhibiting macrophage recruitment and M1 phenotype polarization via AMPKα signaling in HFD-induced obese mice." (PMID 35273574, 2022). "Both in vivo and ex vivo evidence indicates that FNDC5/irisin is involved in the overload/obesity-induced cardiomyocyte hypertrophy by affecting autophagy, inflammation, fibrosis, and oxidative stress." (PMID 36267573, 2022). "Recently, our team identified a new FNDC5 variant in rat INS-1 cell lines while exploring the overlapping effects of GLP-1 and FNDC5 in fighting obesity." (PMID 35321332, 2022). "Fibronectin type III domain-containing 5 (FNDC5), a well-defined myokine and also identified as an adipokine, has a critical role in the modulation of metabolism and protection against obesity." (PMID 35639355, 2022). "The present findings provide preliminary experimental evidence for the potential use of this secreted FNDC5 derivative (sFNDC5) for the treatment of obesity and obesity-related metabolic disorders." (PMID 35321332, 2022). "Plasma irisin levels and muscular FNDC5 expression levels were reduced in patients with obesity and T2DM." (PMID 35745732, 2022). "To test the extent to which secreted FNDC5 derivatives mediate GLP-1’s anti-obesity actions on adipose tissue, we treated mature 3T3-L1 adipocytes with serial concentrations of r-sFNDC5 and GLP-1." (PMID 34869379, 2021). "Diet and physical inactivity play a major role in the genesis of obesity and irisin/FNDC5 modulation." (PMID 34483949, 2021). "In animal models of obesity, upregulation of FNDC5 increased uncoupling protein 1 (UCP1) expression and oxygen consumption, leading to high energy expenditure." (PMID 33817324, 2021). "All these results suggest that deletion of Fndc5 compromises the protection of NR against HFD-induced obesity and hepatic steatosis." (PMID 33754067, 2021). "Fndc5, a well-defined myokine and also identified as an adipokine, has a critical role in modulation of metabolism and protection against obesity." (PMID 32257109, 2020). "In this regard, activation of the PGC-1α–FNDC5–irisin axis is an attractive therapeutic target for ameliorating metabolic diseases such as obesity, insulin resistance, and type 2 diabetes mellitus (T2D)." (PMID 33003348, 2020). "This thermogenic adipomyokine produced by FNDC5 is known to have a potential role in preventing obesity and metabolic syndrome." (PMID 32485990, 2020).
Obesity (continued). "Here, we investigated the role of Fibronectin type III domain containing 5 (FNDC5) in cardiac inflammation and oxidative stress in obesity-induced cardiac hypertrophy." (PMID 30940158, 2019). "FNDC5 attenuates obesity-induced cardiac hypertrophy by inactivating JAK2/STAT3 associated-cardiac inflammation and oxidative stress." (PMID 30940158, 2019). "Our results identify the protective role of FNDC5 in obesity-induced cardiac hypertrophy, which shed additional light on future FNDC5-based therapeutic interventions in obesity-related cardiac abnormalities." (PMID 30940158, 2019). "Potential roles and applications of serum FNDC5/irisin in obesity, chronic kidney disease, Type 2 diabetes mellitus have been investigated in previous studies." (PMID 29522296, 2018). "On the other hand, FNDC5/irisin levels are diminished in people with obesity, hepatic steatosis, metabolic syndrome, and type 2 diabetes mellitus." (PMID 29643769, 2018). "Our data on the expression patterns and functions of FNDC5 in Meishan pigs provide valuable information for further research and development of FNDC5 as a novel treatment of obesity." (PMID 28801552, 2017). "Circulating irisin and adipose tissue FNDC5 were found to attenuate hyperglycemia, visceral adiposity and extramyocellular lipid deposition in obesity and type 2 diabetes in humans." (PMID 28771499, 2017). "Data from this study provide valuable information related to the study on FNDC5 functions and future development of novel treatment for obesity." (PMID 28801552, 2017). "The special effect of FNDC5 on adipose tissue makes it a unique therapeutic target to be studied and developed for treatment of obesity." (PMID 28801552, 2017). "The fibronectin type III domain-containing protein 5 (FNDC5) discovered in 2002 has recently gained attention due to its potential role in protecting against obesity." (PMID 26961074, 2016). "In rodents, overexpression of adenoviral FNDC5 in high-fat diet fed mice results in increased energy expenditure, improved obesity (reduced body weight) and insulin resistance." (PMID 26968837, 2016). "FNDC5/irisin has been recently postulated as beneficial in the treatment of obesity and diabetes because it is induced in muscle by exercise, increasing energy expenditure." (PMID 24864142, 2014). "It is the purpose of this study to examine the combined effects of exercise and obesity on the regulation of myonectin and FNDC5 gene expression." (PMID 25289190, 2014). "This decrease may represent a compensatory mechanism against the elevated FNDC5 expression typically seen in obesity." (PMID 40071055, 2024). "This study demonstrated that obesity significantly increased the expression of the FNDC5 gene." (PMID 40071055, 2024). "Obesity significantly increased the expression of the FNDC5 gene (P = 0.008)." (PMID 40071055, 2024). "Irisin is the product of the Fndc5 gene and mostly diffuses through muscle, subcutaneous white adipocytes, and somewhat from visceral adipocytes in response to exercise, feeding state, and critical states, such as obesity and anorexia." (PMID 39479712, 2024). "Additionally, an increased expression of FNDC5 and irisin alleviates the obesity-induced cardiac inflammation, oxidative stress, and hypertrophic remodeling of the heart." (PMID 36330203, 2022). "As a molecule downstream of MSTN, FNDC5 also plays an important role in obesity and diabetes." (PMID 35639355, 2022). "Our results showed that Rb1 may ameliorate obesity in part through the MSTN/FNDC5 signalling pathway." (PMID 35639355, 2022). "Furthermore, FNDC5 overexpression significantly improved obesity-induced myocardial inflammation, fibrosis, oxidative stress, and cardiac remodeling." (PMID 34840567, 2021). "Also, they demonstrated the beneficial metabolic regulation effect of irisin in vivo, as 20-week high-fat diet-induced obesity was reduced by adenoviral-mediated overexpression of FNDC5 in mice." (PMID 33790964, 2021).
Obesity (continued). "We speculate that inhibiting miR-31-5p to increase FNDC5 may be a therapeutic strategy with some unique advantages in oxidative stress attenuation, vascular remodeling, and hypertension with obesity, diabetes, and atherosclerosis." (PMID 34440213, 2021). "The beneficial role of FNDC5 in the prevention of inflammation and obesity has been hypothesized and needs to be confirmed." (PMID 35008220, 2021). "Thus, the genetic evaluation of FNDC5 can be useful to identify patterns of metabolic health and disease with promising expectation in the treatment of obesity." (PMID 34574727, 2021). "In addition, FNDC5 has been demonstrated to attenuate obesity-induced cardiac hypertrophy by inactivating JAK2/STAT3 associated-cardiac inflammation and oxidative stress." (PMID 33790964, 2021). "Irisin, a newly identified exercise-responsive myokine, which is produced by the proteolytic cleavage of fibronectin type III domain-containing protein 5 (FNDC5), has emerged as a promising therapeutic strategy to combat obesity and obesity-related complications." (PMID 33790964, 2021). "Whether an expression of FNDC5 in human SAT is ectopic or related to obesity remains to be investigated." (PMID 32180552, 2020). "FNDC5 gene deletion aggravated HFD-induced obesity, which was consistent with our recent study." (PMID 30940158, 2019). "The authors proposed that this apparent paradoxical finding could be explained by the leptin resistance condition in obesity, in which leptin may partially lose its ability to downregulate FNDC5." (PMID 31404407, 2019). "Overall, we postulate the following hypothesis: in the course of obesity, secreted factors liberated by obese adipose tissue inhibit FNDC5 and UCP1 expression of differentiating pre-adipocytes promoting enhanced adipogenesis and increasing lipid accumulation." (PMID 29176631, 2017). "Under this context the hypothesis of the present work proposes that FNDC5 might be also produced by the stomach as a major organ involved in energy homeostasis; this secretion at gastric level could be deregulated in obesity." (PMID 26961074, 2016). "Therefore, in obesity the levels of circulating FNDC5 were decreased, together with a decrease in FNDC5 secretion from the stomach." (PMID 26961074, 2016). "Moreover, the observed variations on FNDC5 production by the stomach shown for the first time,in an animal model of obesity supports the potential role of gastric FNDC5 on the gastric chief cells function on energy metabolism." (PMID 26961074, 2016). "Moreover, in the studied models it was found that full length FNDC5 circulating levels detected by western blot in rat plasma with both, polyclonal and monoclonal FNDC5 antibodies, were also decreased in diet-induced obesity." (PMID 26961074, 2016). "Remarkably, results of our study showed the presence of a strong association between the FNDC5 rs3480 (GG) genotype and a reduced risk (protection) of obesity, independent of age, gender and T2DM." (PMID 26968837, 2016). "Thus, augmentation of circulating irisin levels by forced liver expression of FNDC5 using adenoviral vectors improves glucose tolerance and reduces obesity of mice fed on a high-fat diet." (PMID 24864142, 2014). "Finally, adenoviral Fndc5 overexpression in mice increased energy expenditure (probably via enhanced thermogenesis) and improved obesity and insulin resistance induced by high-fat feeding." (PMID 23637927, 2013). "Irisin, derived from cleavage of FNDC5, has been linked to the beiging of WAT in rodents; however, human data on circulating irisin levels remain highly variable, casting doubt on its relevance to local lipid partitioning in skeletal muscle or connective tissues in obesity and T2DM." (PMID 41002965, 2025).